IGF1 (insulin like growth factor 1)
Diseases named in the same sentence as IGF1 in open-access papers (continued):
Sharing a sentence is not in itself a finding about the gene and the disease.
sensorineural hearing loss (6 papers, 2021 to 2025). "Insulin-like growth factor 1 (IGF-1) deficiency is an ultrarare syndromic human sensorineural deafness." (PMID 34359856, 2021). "Moreover, clinical trials have shown that IGF-1 is also effective in treatment for sensorineural hearing loss in humans." (PMID 35720065, 2022). "Homozygous human mutations in IGF1 cause a rare disease (OMIM 608747) characterized by the association of intrauterine and postnatal growth retardation with intellectual deficit and sensorineural deafness." (PMID 34680948, 2021). "A fourth homozygous mutation of IGF1 has been reported, in which the patient did not present with sensorineural deafness." (PMID 34680948, 2021).
Short stature (6 papers, 2015 to 2024). A height below that which is expected according to age and gender norms. "In children with idiopathic short stature, considered to be a variant category of normal children, the GHRd3 is associated with higher circulating IGF-1 in response to GH injection." (PMID 25835289, 2015). "The increment in IGF-1 induced by GH administration in healthy children with idiopathic short stature is normally distributed and can thus be modeled as a continuous quantitative trait." (PMID 25835289, 2015). "Monogenic causes of short stature which are associated with a low serum IGF-I level and normal or high GH levels could comprise the defects of GH1 (bioinactive GH), GHSR (ghrelin receptor), GHR (GH receptor), STAT5B, IGF1, and IGFALS." (PMID 26777041, 2015). "Additionally, in children treated with rhGH, it was found that short children with SGA may have some degree of IGF-1 resistance because they required higher GH-induced IGF-I levels to achieve growth rates similar to those of children with familial short stature or GHD." (PMID 38763958, 2024).
Strabismus (6 papers, 2016 to 2025). A misalignment of the eyes so that the visual axes deviate from bifoveal fixation. "Unilateral implantation of insulin-like growth factor-1 (IGF-1) in adult monkeys was sufficient to reduce eye misalignment, thus showing its potential as a treatment strategy for strabismus." (PMID 32681083, 2020). "This supports the view that there is sufficient plasticity in the adult ocular motor system to allow continuous IGF-1 treatment over months to produce improvement in eye alignment in early-onset strabismus." (PMID 27820875, 2016). "These initial studies were extended using the non-human primate, where sustained release of insulin growth factor -1 (IGF-1) was able to produce a strabismus in infant monkeys as well as improve eye alignment in an adult monkey with a sensory-induced strabismus." (PMID 30142211, 2018). "A second pattern was seen in 2 of the 9 infants treated with either IGF-1 or GDNF studied thus far, where there was a relatively rapid decrease in their exotropia within the first 2–4 weeks, followed by an increase in strabismus angle between 2 and 3 months." (PMID 32681083, 2020). "Our previous work demonstrated that unilateral, but not bilateral, medial rectus muscle treatment with IGF-1 in infant primates was required to produce a strabismus also suggesting central nervous system control of these changes." (PMID 27820875, 2016). "Sustained treatment of an adult strabismic monkey with IGFI resulted in a significant improvement in eye alignment, and sustained treatment with either IGF1 or glial derived neurotrophic factor (GDNF) during the first 3 months of life in nonhuman primates resulted in development of strabismus." (PMID 39330989, 2024).
Wilms tumor (6 papers, 2012 to 2024). An embryonal neoplasm characterized by the presence of epithelial, mesenchymal, and blastema components. "It is unknown if AYA patients with Wilms tumors are more likely to have IGF1R mutations than other patient populations or if AYA patients may benefit from IGF1-targeted therapies." (PMID 26328274, 2015).
acanthosis nigricans (5 papers, 2021 to 2025). A melanotic cutaneous lesion that develops in the axilla and other body folds. "Additionally, the use of recombinant human IGF-1 (rhIGF-1) was associated with improvements in acanthosis nigricans, and levels of plasma glucose, insulin, fructosamine and HbA1c in patients with extreme insulin resistance syndromes, including congenital generalized lipodystrophy (CGL)." (PMID 40520449, 2025). "Insulin and insulin-like growth factor-1 (IGF-1) can stimulate the growth of skin cells and the production of melanin, leading to the development of acanthosis nigricans." (PMID 37313065, 2023).
age-related hearing loss (5 papers, 2017 to 2025). "Research has shown that low levels of IGF-1 may contribute to the progression of age-related hearing loss." (PMID 40226444, 2025). "In the elderly, the expression of IGF-1 in the inner ear gradually diminishes, leading to inflammatory responses, a failure of the cell renewal mechanism, and an acceleration of presbycusis." (PMID 40226444, 2025). "A potential interpretation of the observed differential effect of IGF-1 according to age is that the protective role of IGF-1 may not apply as much in presbycusis, where vascular damage may be a stronger risk factor." (PMID 28646237, 2017).
Allergy (5 papers, 2017 to 2022). An allergy is an immune response or reaction to substances that are usually not harmful. "In fact, we excluded a priori other pituitary axis impairments in order to include a highly selected population to fit our primary aim, which was the evaluation of the link between GH/IGF1 axis, pituitary morphology and Ni allergy." (PMID 33419306, 2020). "Following this line of reasoning, allergy-induced M2A polarization, with its increased production of IGF1, BDNF and further growth factors, would contribute to ASD via inhibition of normal pruning of synapses." (PMID 29232822, 2017).
androgenetic alopecia (5 papers, 2020 to 2025). "IGF-1 supports hair growth and is crucial for the hair follicle cycle and development in transgenic mice, with its expression being associated with androgenetic alopecia." (PMID 39518915, 2024). "Its clinical relevance in androgenetic alopecia and alopecia areata has been demonstrated by topical or targeted delivery of IGF-1 to increase hair density and improve follicle structure." (PMID 41020895, 2025). "Both preclinical models and clinical evidence highlight IGF-1 as a promising therapeutic option for conditions like androgenetic alopecia (AGA), where IGF-1 levels are typically diminished." (PMID 41020895, 2025). "IGF-1 promotes hair growth and plays an important role in the HF cycle and development in transgenic mice; with expression of IGF-1 correlated with androgenetic alopecia." (PMID 33375217, 2020). "Importantly, IGF-1’s clinical relevance is illustrated in androgenetic alopecia (AGA), where decreased IGF-1 expression by DP cells in balding scalp regions correlates with follicular degeneration and anagen shortening." (PMID 41020895, 2025).
bone fracture (5 papers, 2020 to 2024). "Lower serum IGF-1 levels are correlated with older postmenopausal women and increase the risk of bone fracture." (PMID 33333838, 2020). "Another study found that IGF-1 induced both ALP activity and minerals formation in BM-MSCs superior to BMP-7, even if the difference was not statistically significant suggesting IGF-1 represents a more promising candidate for clinical application in bone fractures." (PMID 34940355, 2021).
carcinoid tumor (5 papers, 2013 to 2017). A slow growing neuroendocrine tumor, composed of uniform, round, or polygonal cells having monotonous, centrally located nuclei and small nucleoli, infrequent mitoses, and no necrosis. "Immunohistochemically, a typical carcinoid (TC) was seen with low proliferation index and abundant IGF-1 expression." (PMID 27349224, 2016). "The extent to which carcinoid tumors are regulated by other hormones is not clear; however, they do express receptors for IGF-1, somatostatin, and gastrin overproduction was linked to the development of at least a subtype of carcinoid tumors." (PMID 26290759, 2015).
cholestasis (5 papers, 2005 to 2017). Impairment of the bile flow caused by obstruction within the liver, or outside the liver in the bile duct system. "The implication is that preservation of both Igf1 and Hnf6 axes is important to hepatic survival responses against apoptosis and cholestasis." (PMID 27936029, 2016). "Hnf6 is therefore necessary for GH broad protection against apoptosis and cholestasis during BDL injury, independently of Igf1." (PMID 27936029, 2016). "Other hormones, GH or/and IGF-1 or/and FT4, might participate to the onset and the persistence of cholestasis in PSIS, as supported by experimental studies: hypophysectomy in rats not only reduced bile acid synthesis and bile flow but also decreased bilirubin and bromosulfophtalein transport." (PMID 26829045, 2016). "Contrasting with these findings, we did not identify any infant with isolated GH deficiency and suffering from cholestasis in this series, and IGF-1 and FT4 levels were not different between patients with and without cholestasis." (PMID 26829045, 2016).
craniosynostosis (5 papers, 2011 to 2023). Craniosynostosis is defined as the premature fusion of one or more cranial sutures leading to secondary distortion of skull shape resulting in skull deformities with a variable presentation. "Taken together, these data suggest that activation of the IGF1 pathway may predispose to the development of craniosynostosis." (PMID 31442251, 2019). "While our data suggest that dysregulation of the TWIST1/RUNX2 and IGF1/Akt pathways may predispose humans to craniosynostosis, further translational research is necessary before the development of clinical utility." (PMID 31442251, 2019). "These polygenic mouse models reinforce, in-vivo, that the combination of activation of the IGF1 pathway and disinhibition of the RUNX2 pathway leads to an increased risk of developing craniosynostosis and serves as a model of human SSC." (PMID 31442251, 2019). "The IGF1/IGF1R pathway is critical for normal bone growth and density and has been implicated in the etiology of craniosynostosis." (PMID 31442251, 2019). "These mouse models demonstrate an increased frequency and severity of craniosynostosis and support the hypothesis that combined dysregulation of the TWIST1 and IGF1 pathways could contribute to an increase risk in humans." (PMID 31442251, 2019). "In this study, we describe compound heterozygous mutant mice with genetically altered expression of Igf1 and Gsk3β and disinhibition of Runx2, that result in a significantly increased rate or severity of craniosynostosis when compared to mice with each genotype in isolation." (PMID 31442251, 2019). "In this manuscript we present data from mouse cross-breeding experiments designed to explore possible polygenic inheritance of craniosynostosis using Twist1/Igf1 and Twist1/Gsk3β compound heterozygotes to test hypotheses generated from our previous human expression data." (PMID 31442251, 2019). "While previous research has indicated crosstalk between the Htra1/Igf1, Akt, and Wnt pathways after thyroid exposure leading to a synergistic effect, further characterization of the signaling cascade is required to determine how thyroid exposure results in craniosynostosis." (PMID 27959899, 2016). "While none of the Igf1(+/tg) or Igf1(tg/tg) transgenic mice developed craniosynostosis, 23% of the Gsk3β(+/-) mice displayed craniosynostosis and/or presumed hydrocephalus, a previously undescribed phenotype with incomplete penetrance." (PMID 31442251, 2019). "While none of the Gsk3β(+/-)/Igf1(+/tg) mice that survived to P28 showed suture fusion, the reduced number of offspring with this genotype precludes our ability to define the true craniosynostosis rate." (PMID 31442251, 2019).
Delayed puberty (5 papers, 2009 to 2024). Passing the age when puberty normally occurs with no physical or hormonal signs of the onset of puberty. "In our study there were also eight cases of RCC in people with a short stature who had low levels of GH, IGF-1, and LH and were diagnosed with delayed puberty or growth hormone deficiency, both of which may result from a RCC." (PMID 35295993, 2022). "Those with short stature were further evaluated using insulin-like growth factor 1 (IGF-1), bone age, and thyroid profile, while those with delayed puberty were evaluated using sex hormones and pituitary gonadotropins assay." (PMID 38724932, 2024). "A lead-induced decrement in IGF-1 may contribute to gonadotropin inhibition and pubertal delay." (PMID 23632160, 2013).
Down syndrome (5 papers, 2022 to 2025). "Evidence has shown that IGF1 deficiency was associated with the progression of nervous system diseases, such as Down’s syndrome and Parkinson." (PMID 40626048, 2025). "We believe that the therapeutic potential of IGF-1/IGF-1R signaling remains very promising and should be further explored, as for example, in Down's syndrome." (PMID 39638246, 2024). "VAD, low serum retinol, and low insulin-like growth factor 1 (IGF-1) are thought to contribute to a poor immune system and poor growth and development in children with Down syndrome (DS)." (PMID 38226115, 2023).
ependymoma (5 papers, 2013 to 2025). A WHO grade II, slow growing tumor of children and young adults, usually located intraventricularly. "Activated TAM-MGs produce insulin-like growth factor 1 (IGF1), which functions through autocrine/paracrine signaling to regulate the development and progression of pediatric ependymomas." (PMID 40948940, 2025).
experimental autoimmune encephalomyelitis (5 papers, 2012 to 2023). An autoimmune demyelinating disease of the central nervous system that is produced experimentally in animals by the injection of homogenized brain or spinal cord in Freund's adjuvant. "The doses used in our study have been the same as in experimental autoimmune encephalomyelitis mice where positive effects on inflammatory, demyelinating, and demyelinated lesions have been seen when using IGF-1." (PMID 22778966, 2012). "Previous studies found that a chronic elevation of IGF1 expression exacerbated mouse experimental autoimmune encephalomyelitis (EVE), which might be partly mediated by the expansion of T cells." (PMID 26980945, 2016).
gastric ulcer (5 papers, 2013 to 2022). An ulcerated lesion in the mucosal surface of the stomach. "Our studies demonstrated that IGF-1 is upregulated in the gastric ulcer margin and that exogenous IGF-1 promotes gastric re-epithelization, proliferation, and COX-2 expression via the PI3K pathway." (PMID 34440733, 2021). "Pro-inflammatory cytokines like tumor necrosis factor-α (TNF-α), Interleukin-1β (IL-1β), Interleukin-6 (IL-6) and growth factors including insulin like growth factor-1 (IGF-1) play an important role in the pathogenesis of chronic diseases like autoimmune diabetes and gastric ulcers." (PMID 24192345, 2013).
gynecologic cancers (5 papers, 2014 to 2020). "Epidemiological, clinical, and experimental data also shore up the evidence that IGF1 is an important players in general gynecological cancers, and particularly in endometrial tumors." (PMID 32641130, 2020). "The insulin-like growth factor 1 (IGF1) pathway has been proven to contribute to the suppression of immune tumor microenvironment (TME) in gynecologic cancers." (PMID 33274204, 2020). "Epidemiological as well as clinical and experimental data identified the insulin-like growth factors (IGF1, IGF2) as important players in gynecological cancers in general, and endometrial tumors in particular." (PMID 24904527, 2014).
Gynecomastia (5 papers, 2022 to 2025). Abnormal development of large mammary glands in males resulting in breast enlargement. "A cohort study showed that increased IGF-1 levels are associated with gynecomastia in pubertal boys." (PMID 40002676, 2025). "Ten key genes associated with gynecomastia were identified, including IGF1, TGFB1 and AR, alongside 12 candidate drugs with promising binding affinities, such as yifenidone, conteltinib and vosilasarm." (PMID 40002676, 2025). "The GH/IGF-1 axis is also thought to interact with thyroid hormones, contributing to the development of pubertal gynecomastia." (PMID 40002676, 2025). "The presence of low IGF-1 levels, normal pituitary imaging, and gynecomastia highlights the need for individualized evaluation rather than reliance on classical diagnostic criteria." (PMID 41552116, 2025). "This case represents a probable diagnosis of PDP with rare endocrine involvement presenting as gynecomastia and low IGF-1 levels." (PMID 41552116, 2025). "In rare cases, hormonal abnormalities such as gynecomastia and altered insulin-like growth factor-1 (IGF-1) levels have been described, adding complexity to diagnosis." (PMID 41552116, 2025). "The stable IGFBP-3 levels observed in PG patients further emphasize IGF-1’s independent and distinct role in the pathogenesis of gynecomastia." (PMID 39797240, 2024). "Crucially, insulin-like growth factor-1 (IGF-1) is a key mediator in pubertal gynecomastia (PG), directly driving breast tissue proliferation during critical growth phases." (PMID 39797240, 2024). "Locally produced IGF-1 may be more relevant to the development of gynecomastia than circulating IGF-1." (PMID 39797240, 2024). "In Mieritz’s study, both IGF-1 and estrogen were elevated in boys with gynecomastia." (PMID 39797240, 2024). "The estradiol-to-testosterone ratio showed no significant changes, highlighting IGF-1 as a key factor in the pathogenesis of pubertal gynecomastia." (PMID 39797240, 2024).
Headache (5 papers, 2022 to 2024). Cephalgia, or pain sensed in various parts of the head, not confined to the area of distribution of any nerve. "A weak positive correlation, but statistically insignificant, was found between the IGF-1 levels and the intensity of the symptoms of headache on PASQ (Spearman r coefficient = 0.21)." (PMID 36577870, 2022). "Headache almost disappeared in all patients (in 5/6 after the first injection) and reappeared with pathologic IGF-1 levels after PAS-LAR withdrawal in one irradiated patient." (PMID 35744057, 2022).
hemorrhagic stroke (5 papers, 2010 to 2021). A stroke caused by a bleed on the brain. "Administration of IGF-1 following ischemic and/or hemorrhagic stroke attenuates microglial activation, inflammation, and ROS." (PMID 34887742, 2021). "In addition, the microglial M2 polarization mediated by the secretory factors, insulin-like growth factor-1 (IGF-1) of stem cells, was considered to be a possible mechanism for stem cells improved hemorrhage stroke prognosis." (PMID 33841103, 2021).
hyperostosis (5 papers, 2022 to 2025). Excessive thickening of bone. "Excessive GH levels and, secondarily, insulin-like growth factor 1 (IGF-I) cause a range of complications, from changes in appearance to soft tissue and bone hypertrophy, leading to systemic disorders that result in shortened survival rates and reduced quality of life." (PMID 40149642, 2025). "Genetic factors in hyperostosis include Proteus Syndrome, a rare condition characterized by overgrowth in several tissue systems, osteoprotegerin (OPG), bone morphogenetic protein (BMP), and insulin-like growth factor 1 (IGF-1)." (PMID 35205806, 2022).
hyperparathyroidism (5 papers, 2015 to 2025). Hyperfunction of the parathyroid glands resulting in the overproduction of parathyroid hormone. "These include inflammation, acidosis, hemodialysis (HD) treatment, hyperglucagonemia, hyperparathyroidism, endocrine disorders such as resistance to insulin and insulin-like growth factor-1(IGF-1), and so on." (PMID 33986663, 2021).